CD4 (CD4 molecule)
Diseases named in the same sentence as CD4 in open-access papers (continued):
Sharing a sentence is not in itself a finding about the gene and the disease.
infection (continued). "In order to determine if active MoDC infection was required for CD4+ T cell stimulation, T cells were stimulated once or twice with either live (L) or inactivated (gamma irradiated)(dead) (D) YFV." (PMID 27191161, 2016). "The expression of Ki67 was significantly increased in CD38+ CD4+ T cells compared to CD38- CD4+ T cells prior to and during infection (p < 0.0001)." (PMID 27662621, 2016). "Conversely, the expression of the anti-apoptotic marker Bcl2 was significantly reduced in CD38+ CD4+ T cells compared to CD38- CD4+ T cells both prior to and at peak infection (p = 0.002)." (PMID 27662621, 2016). "These constructs were then transfected into Cf2-Luc cells with CD4 and evaluated for the ability to support infection by X4- (HxB2) or dual-tropic (R3A) HIV-1s." (PMID 27855210, 2016). "In agreement with the reporter data, Ag-experienced splenic CD4+ T cells obtained on day 7 of infection produced high levels of IFN-γ and IL-10 protein." (PMID 27630165, 2016). "The deficiency in CD11b+ DCs however, is then overcome by the massive influx of monocyte-derived DCs as well as a novel CD11b+ DCs that likely rescue the CD4+ T cell response at later time-points during the course of the infection." (PMID 27030971, 2016). "After infection or administration of a contact sensitizing agent, there is a sustained increase in skin CD4+ T-cell content, which is confined to the clusters, with a concomitant CCL5-dependent increase in CD4+ T-cell recruitment." (PMID 27160938, 2016). "More recently, a skin-resident CD4 T cell memory subset, similarly generated in mice who resolved their primary infections, was shown to rapidly produce IFN-γ at the site of secondary challenge and boost the recruitment circulating T cell memory subsets." (PMID 26932389, 2016). "Whereas both CD4+ and CD8+ T cells produced IFN-γ during T. cruzi infection, only CD4+ T cells were positive for IL-22 at day 14 post infection after unspecific or antigen-specific stimulation." (PMID 27650379, 2016). "An enhancement in the co-expression of CD25+GITR+ or CD25+CD62L+ was also observed after infection among CD4+Foxp3+ cells." (PMID 26745276, 2016). "Proliferating CD8 and CD4 T-cells were low early after infection, then increased until T11–T13 and dropped down just prior to viral clearance, suggesting an ongoing antigen-driven proliferation." (PMID 27031961, 2016). "The Th1 response was maintained after infection because IFN-γ production is based mainly on CD4+ T cells." (PMID 27340562, 2016). "In these studies, we found C. trachomatis challenge infection was eradicated significantly faster than primary infection, and that CD4+ T cells were chiefly responsible for this enhanced clearance." (PMID 27606424, 2016). "In vitro studies have shown that DC can also be infected cell-free with highly-concentrated viral supernatants, and these infected DC mediate efficient cell-cell contact-dependent infection and transformation of CD4+ T-cells." (PMID 27005656, 2016). "When assessed as percentages, CD4+ T cells appeared to decrease in MRLN after infection, and B cells remained relatively constant." (PMID 27315117, 2016). "DNA methylation levels at the IFNG 5′ promoter were significantly lower in CD4+ T lymphocytes during infection with M. bovis." (PMID 27507428, 2016). "Similar to the GI tract, tissues of the FRT contain partially activated, memory CD4+ T cells that can serve as targets for HIV and experimental infection of rhesus macaques with SIV has shown a rapid depletion of CD4+ T cells." (PMID 27438728, 2016). "Our results also demonstrate the down-regulation of transcription factor FOXO-1, and up-regulation of its controlling microRNA, i.e., miR-182, in CD4+ T cells isolated at day 12 post infection from Cm infected mice compared to mock infected animals." (PMID 27556515, 2016).
infection (continued). "In contrast, infection of PHA-IL2 activated CD4+ T cells resulted in a small but non statistically significant reduction in the levels of integration following infection with NL4-3 ΔNF-κB1 and ΔNF-κB1,B2 viruses." (PMID 27459960, 2016). "Manipulating CD8+ and CD4+ T cell proliferation rates, as well as DC migration early on during infection can determine the difference between bacterial clearance vs. uncontrolled bacterial growth and dissemination." (PMID 28989808, 2016). "To study the clonotypic composition of an antiviral CD4+ T-cell response, we used infection of wild-type (WT) B6 mice with FV." (PMID 26728651, 2016). "CD38+ CD4+ T cells stained negatively for the apoptotic marker Annexin-V and the viability stain propidium iodide (Pi) prior to infection (98.4±0.5% Annexin-V-, 99.8±0.5% Pi-) and during infection (98.8±0.8% Annexin-V-, 99.8±0.2% Pi-)." (PMID 27662621, 2016). "Fourteen days after direct infection of resting CD4 T cells, we sorted cells into 4 groups based on GFP fluorescence intensity." (PMID 26728316, 2016). "Mice were infected with P. murina and groups of mice were depleted of CD4+ T cells, CD8+ T-cells, CD4+/CD8+ T-cells, macrophages, and CD4+ T-cells/macrophages every 6 days with depletion occurring prior to secondary infection (2°)." (PMID 27242785, 2016). "Human CD4 T cells are constantly exposed to IL-12 during infections and certain autoimmune disorders." (PMID 27280403, 2016). "These cells can subsequently pass the virion to activated CD4+ T-lymphocytes, a process termed trans-infection." (PMID 26808476, 2016). "While much is known in CD8+ (killer) T cells, the expansion of CD4+ (helper) T cells during an infection is less well understood at the cellular and molecular levels." (PMID 27176874, 2016). "HSV resulted in extensive T-cell infiltration of CD4+ T cells at the site of infection, with most being lost by day 30 after inoculation." (PMID 27160938, 2016). "A comparison of infection profiles of infected CD4 T cells at the time of activation (10–13 days post-infection) frequently showed that the percent infection of shCTRL- expressing cells was markedly higher than shPTB-expressing cells." (PMID 27513449, 2016). "We perform ex vivo single-cell RNA-sequencing of CD4+ T cells during a mouse model of infection that elicits a type 2 immune response and infer that the differentiated, cytokine-producing cells cycle faster than early activated precursor cells." (PMID 27176874, 2016). "The CD4 count at the time of infection was known for all HIV patients; all but one had <270 cells/μL, and 7/13 had < 200 cells/μL." (PMID 27487784, 2016). "Over time, the mean fluorescence intensity of T cells was roughly equivalent, until CD4+ T cells acquired higher MFI at late times in infection." (PMID 26991092, 2016). "In this case, a significant increase in CD3 and CD4 transcription levels was observed in response to the virus at day 1 post-infection and also at day 3 in the case of CD4." (PMID 26808410, 2016). "Protective immunity to secondary infection requires the cooperation of CD4 T cells and Salmonella-specific antibody responses." (PMID 27999159, 2016). "In sum, these experiments support a role for NFAT in Vpr-mediated infection of unstimulated CD4+ T cells." (PMID 27383627, 2016). "When given in the first 3 days of infection, treatment with E6446 inhibited CD4+ and CD8+ T-cell activation and IFNγ production." (PMID 27808089, 2016). "Expression of TGF-β over the course of infection was relatively stable in CD4 and the CD8 T cells in the LCMV and LCMV-METH groups." (PMID 27760221, 2016). "Following SIVMAC251 infection, absolute CD4 count in peripheral blood decreased rapidly in the majority of the animals except GN91, in which CD4+ T-cell count decreased after 150dpi." (PMID 27903274, 2016).
infection (continued). "It is worth mentioning that the susceptibility of TKO mice occurred in parallel to undetectable changes in presentation of MHC II-restricted epitopes to CD4+ T cells and in the generation of CD4effector cells during infection." (PMID 27128676, 2016). "Following most viral dynamics models, we assumed that these cells are produced at a rate determined by the product of the viral load, the density of target CD4 cells, the infectivity, and the probability of infection resulting in latency." (PMID 27119536, 2016). "Previous work from our group identified a TLR2-mediated increase in HIV infectivity of CD4+ T cells following infection of PBMC with M. bovis BCG compared to M. smegmatis." (PMID 26807859, 2016). "We interpret these dynamics as hyperacute expansion of the CD4+CCR5+ target cell compartment with subsequent contraction into the chronic phase of infection due to a combination of virus replication and withdrawal of microbial products." (PMID 27926931, 2016). "Other reports have suggested that certain erythrocyte lipids promote viral membrane fusion with CD4+ cells and thus facilitate infection." (PMID 26900853, 2016). "Flow cytometry demonstrated a decrease in CD4+ cells over the course of the infection, confirming the productive infection of CD4+ T cells." (PMID 27834891, 2016). "The characteristic CD4 Th1 profile observed after systemic immunization was maintained after infection by lung-infiltrating antigen-specific CD4+ T cells that expressed IFN-γ and TNF-α, alone or in combination." (PMID 27525409, 2016). "Consistent with this, we show that the majority of the skin CD4+ T cells that produce the antiviral cytokine IFNγ upon secondary infection with HSV are localized to hair follicles." (PMID 27160938, 2016). "For example, high CD8+ T cell proliferation rates in the lymph node result in overall lower levels of effector CD4+ T cells at the granuloma site (i.e., Tγ cells at the site of infection)." (PMID 28989808, 2016). "Here, we report infection of cattle with FMDV A24 Cruzeiro leads to a rapid decline in immature CD4+MHC class II− pDC during peak viremia." (PMID 27008425, 2016). "During infection, or in the context of autoimmunity, however, DCs play a pivotal role in the activation of CD4 and CD8 T cells." (PMID 27122656, 2016). "The results showed that supernatant from the R848-treated monocytes blocked infection of the activated CD4+ T cells." (PMID 27905985, 2016). "Cell-to-cell transmission is the predominant mode of HIV-1 spread in CD4+ T lymphocytes and is thougt to be 100–1000 times more efficient than infection by cell-free virus." (PMID 27598717, 2016). "Our model implied that B-cell presentation should promote TCR diversity not only in response to infection or immunization, but also in any setting where CD4+ T-cell clonotypic competition is likely to operate based on TCR avidity." (PMID 26728651, 2016). "In contrast, GBS-infected mice have been reported to display enhanced % of central memory CD4+ T cells following a boost-infection under the same experimental conditions." (PMID 27905502, 2016). "Employing this model and adoptive transfer we describe here that CD8+ and CD4+ T cells enter the CNS and that both T cell populations are protective against this infection and R. typhi-induced disease." (PMID 27875529, 2016). "In our study, IFN-γ production and CD4+ memory T cell expansion were observed in spleen and lung cells isolated from mice treated with Rv3628 at various time points after infection with Mtb strains (H37Rv and Beijing-K)." (PMID 27097115, 2016). "The viral loads and CD4/CD8 ratios tend to change in opposite directions during the course of infection." (PMID 27708644, 2016). "During FMDV, strain O1 Manisa infection of cattle, we observed a statistically significant (50%) decline in the levels of MHC class II on CD11c+ cDC, CD11c− cDC, and CD4+ pDC until day 4 post-infection, when they returned to pre-infection levels." (PMID 27008425, 2016).
infection (continued). "IRF-1 is downregulated and K48 polyubiquitinated in HIV-1-infected Jurkat T cells and during HIV-1 de novo infection of human primary CD4+ T cells." (PMID 27795392, 2016). "By contrast, epicutaneous infection led to significantly higher expression of tissue-homing molecules in CD4 helper T cells." (PMID 27524984, 2016). "We describe a novel approach to confer HIV-resistance to CD4 T cells using peptides from the HIV-1 gp41 heptad repeat-2 (HR2) domain to inhibit infection." (PMID 27855210, 2016). "B2m−/− neonates were more susceptible to lethal infection and, notably, most deaths occurred prior to 14 days post infection—i.e., well before the time that CD4−/− neonates begin to succumb." (PMID 28119902, 2016). "How infection can be maintained, when given the short half-lives of CD4+ T-cells (less than two days), remains a puzzle." (PMID 28936255, 2016). "Reduced RAL sensitivity of coculture infection was also confirmed with transmission between purified autologous CD4+ T cells using a 2-hour infection window." (PMID 27812216, 2016). "In contrast to human immunodeficiency virus (HIV), cell-free infection of CD4+ T-cells with HTLV-1 is very inefficient." (PMID 27005656, 2016). "We believe that the current study supports a previous report and a model whereby IL-17 produced by neutrophils and CD4+ T cells plays a critical role in the early phase of infection by contributing to pathogen clearance." (PMID 27848994, 2016). "This increase continued through day 14 post-infection resulting in more than an eight-fold increase in total CD4+CD25+FoxP3+ T cells." (PMID 27175511, 2016). "The number of induced Treg cells (CD4+Foxp3+) was higher in the Lb than in the La infection at 4 weeks PI but decreased in the DLN of mice infected with Lb during the evolution of the infection." (PMID 27073297, 2016). "Taken together, our data showed that IFNγ+IL10+ CD4+ T cells are present during the first-ever symptomatic infection with P. falciparum in naïve individuals as well as in individuals who were last exposed > 5 years ago." (PMID 27802341, 2016). "In accordance with our previous findings, we observed a significant reduction in miR-182 expression in genital tracts or in CD4+ T cells isolated from miR-182 inhibitor treated mice compared to control-treated or mock treated mice post Cm infection." (PMID 27556515, 2016). "Altogether these results suggest that CD8+ T-cell-derived CCL5 plays a significant role in maintaining elevated numbers of CD4+ T cells in the skin long term following an infection." (PMID 27160938, 2016). "Instead, latency, gene expression and virus production from unintegrated HIV-1 DNA are natural and possibly unavoidable consequences of the direct infection of resting CD4 T cells." (PMID 26728316, 2016). "In other words, endogenous CD4+CD25+ Tregs were able to suppress the effective protection immunity response of the host to invading pathogens, resulting in long-lasting pathogenic infection." (PMID 26901645, 2016). "This group of drugs prevents the infection by blocking the chemokine receptor 5 (CCR5) antagonist receptor present on CD4 cells." (PMID 27054050, 2016). "We used longitudinally observed levels of residual viremia and CD4 counts observed for each patient, and took bounds on the rates of infection and entry into latency during cART obtained from previous studies." (PMID 27119536, 2016). "After complete resolution, CD8+ memory T cells are responsible for secondary infection control in addition to CD4+ T cells." (PMID 27092123, 2016). "In agreement, at week 2 post-infection a reduced frequency of infiltrating CD4+ T cells expressing deactivation or suppressive molecules (CTLA4, GITR, ICOS) were seen in the lungs of pDC-depleted mice." (PMID 27992577, 2016). "Our studies provide definitive evidence that CD4+ T cells become functionally exhausted early after infection, and subsequently, CD8+ T cells also show signs of dysfunction." (PMID 26967901, 2016).
infection (continued). "Mycoplasma lung disease is immunopathologic, with CD4+ Th cells determining both disease severity and resistance to infection." (PMID 27175511, 2016). "Viral capture facilitates the release of trapped viruses at a cell-to-cell contact zone promoting the trans-infection of CD4+ T cells." (PMID 27510803, 2016). "Profound suppression of HIV-1 production and infection was reported in different cell types including latently infected CD4+ T cell lines, primary CD4+ T cells and induced human pluripotent stem cells." (PMID 27230886, 2016). "Pulmonary inflammatory response triggered by infection with 107 CFU of the cda1Δ2Δ3Δ mutant was followed by a specific increase in the recruitment of Th1 CD4+ T cells in the infected mouse lung." (PMID 27165801, 2016). "This reduction in the number of CD4+ T cells persisted after challenge infection and gradually came back to normal by 6 to 8 days post-boost infection." (PMID 27905502, 2016). "We report here that R3A infection induced depletion of both infected and uninfected “bystander” CD4 T cells, and treatment with CCR5 antagonist TAK-779 inhibited R3A-induced bystander CD4 T cell depletion without affecting virus replication." (PMID 27026376, 2016). "This is highlighted by the fact that exposure to Pneumocystis is ubiquitous in humans and that the memory response to infection is often called into play in the context of CD4+ T-cell depletion (HIV infection)." (PMID 27242785, 2016). "The resolution of the infection caused by HAV is influenced by the dynamics of T lymphocytes, particularly CD4+ TLs and Tregs." (PMID 27578921, 2016). "We describe here interrelationships between viral replication, immune activation, and functional CD4 T cell responses in early infection." (PMID 27746782, 2016). "In contrast, predicted Mtb-specific T cell levels in blood do allow us to distinguish infection outcomes (active vs latent) by ~300 days post infection (both CD4+ and CD8+)." (PMID 27065304, 2016). "Some studies, but not all, report that pre-conditioning resting CD4+ T-cells with the chemokine CCL19 enhanced direct infection of resting CD4+ T-cells in vitro." (PMID 27383184, 2016). "Nevertheless, the in vivo CD4+ T cell response later recovers and the mice are able to control infection, and at this stage antibodies seem to play an important role in the parasitemia control." (PMID 27110574, 2016). "The successful infection of CD4+ T cells was confirmed by detecting p24 antigen in the supernatant at several time points post infection." (PMID 27145859, 2016). "Instead, the virus is transmitted to complement receptor bearing cells such as macrophages and CD4+ T cells allowing infection to take place." (PMID 28066413, 2016). "The results consist with recent findings that CD4+ T cells are required to contain extrapulmonary TB and rapid TB progression after infection." (PMID 26959228, 2016). "Somewhat unexpectedly, high abundance HAMB that induced significantly high levels of productive infection and CD4 T cell death similar to E. coli facilitated only minimal increased LP T cell activation." (PMID 26762145, 2016). "Given the mechanism of productive infection by HIV-1 of CD4+ T lymphocytes, events in schistosomes would have taken place in concert with cellular factors." (PMID 27764257, 2016). "With respect to lymphoid cell populations later in the infection, CD4+ subsets decreased significantly in the highly virulent C. psittaci HJ group." (PMID 27405059, 2016). "CD4+ T cells were a major source of IL-10 in all examined organs during malaria infection, with the exception of the spleen after day 14 of infection." (PMID 26459508, 2016). "Mechanistically, we identified that type I IFNs directly induce T-bet and Blimp-1 expression in CD4 T cells responding to Plasmodium blood-stage infection, which amplifies their production of IL-10 and IFN-γ." (PMID 27732671, 2016).